YTHDF3 (YTH N6-methyladenosine RNA binding protein F3)
Diseases named in the same sentence as YTHDF3 in open-access papers (continued):
Sharing a sentence is not in itself a finding about the gene and the disease.
Wilms tumor (1 paper, 2024). An embryonal neoplasm characterized by the presence of epithelial, mesenchymal, and blastema components. "The mechanism underlying this effect requires additional investigation, possibly because the variant of YTHDF3 rs2241753 affects the expression of its downstream Wilms tumor-associated genes." (PMID 39440064, 2024). "The YTHDF3 rs2241753 AA genotype was significantly associated with an increased risk of Wilms tumor in females (adjusted OR=1.74, 95% CI=1.05-2.88, P=0.033)." (PMID 39440064, 2024). "Our study presents a multicenter analysis with a large sample size, demonstrating for the first time the relationship between YTHDF3 SNPs and Wilms tumor susceptibility." (PMID 39440064, 2024). "The YTHDF3 rs2241753 AA genotype and the presence of 1-3 risk genotypes were significantly associated with increased Wilms tumor risk in female children." (PMID 39440064, 2024). "A five-center case‒control study including 414 patients and 1199 controls was conducted to explore the relationship between YTHDF3 gene polymorphisms and Wilms tumor susceptibility." (PMID 39440064, 2024). "Third, the number of SNPs in the study was relatively small, indicating the need to include more YTHDF3 SNPs and analyze their combined effects on Wilms tumor risk." (PMID 39440064, 2024). "Our data indicate that rs2241753 in YTHDF3 is significantly associated with an increased risk of Wilms tumor in female children." (PMID 39440064, 2024). "Our study revealed that the YTHDF3 rs2241753 AA genotype has an enhancing effect on Wilms tumor susceptibility in female children." (PMID 39440064, 2024). "The objective of this study was to investigate the association between YTHDF3 polymorphisms and Wilms tumor susceptibility in Chinese children while providing a theoretical basis for subsequent studies." (PMID 39440064, 2024). "Currently, the relationship between YTHDF3 gene variants and cancers such as Wilms tumor remains unclear." (PMID 39440064, 2024). "However, further analysis is needed to understand the relationship between the YTHDF3 gene SNPs and the risk of Wilms tumor." (PMID 39440064, 2024). "The relationship between YTHDF3 gene polymorphisms and Wilms tumor remains incompletely understood." (PMID 39440064, 2024). "Finally, additional protein-level studies are needed to determine the potential mechanisms by which YTHDF3 SNPs influence Wilms tumor susceptibility." (PMID 39440064, 2024). "In conclusion, our findings suggest that the presence of the YTHDF3 rs2241753 AA genotype or 1-3 YTHDF3 risk genotypes may increase the risk of Wilms tumor occurrence in female children." (PMID 39440064, 2024). "Here, we sought to investigate the potential role of YTHDF3 gene SNPs in the risk of Wilms tumor." (PMID 39440064, 2024). "This may be because the effect of YTHDF3 SNPs on Wilms tumor is relatively subtle or population specific." (PMID 39440064, 2024). "However, the association between YTHDF3 gene polymorphisms and Wilms tumor susceptibility has not been previously reported." (PMID 39440064, 2024).
tumor (90 papers, 2018 to 2025). "In another study in GC, YTHDF3 was found to be associated with poor prognosis and tumor immune infiltration." (PMID 40366509, 2025). "During the observation of flank xenografts in BALB/c nude mice for 28 days, YTHDF3 knockdown significantly delayed tumor progression, as the volume of YTHDF3-deficient tumors was significantly decreased compared with that of control tumors." (PMID 40406242, 2025). "For example, modified by m6A and recognised by YTHDF3, some circRNAs were reported to encode short peptides under the regulation of eukaryotic translation initiation factor 4 gamma 2 (eIF4G2), promoting tumour progression." (PMID 38073586, 2023). "TIMER and CIBERSORTx were employed to analyze the association between YTHDF3 and tumor-infiltrating immune cells." (PMID 35755811, 2022). "In brain metastasis of breast cancer, transcripts associated with brain metastasis are enriched by YTHDF3 and promote cancer cells to interact with cells in the tumour microenvironment, benefiting angiogenesis and metastasis." (PMID 35004679, 2021). "Together, these results clearly show that the expressions of GAS5 are reduced in CRC tissues compared with adjacent tissues, and lower GAS5 expressions are associated with elevated expressions of YAP and YTHDF3 in tumor tissues from CRC patients." (PMID 31619268, 2019). "On the basis of these findings, we hypothesized that YTHDF3 might regulate the development of the ITME by influencing the accumulation of tumor-associated macrophages (TAMs), myeloid-derived suppressor cells (MDSCs), and Tregs." (PMID 41453852, 2025). "In cancer biology, YTHDF3 has been linked to tumor metastasis and immune evasion." (PMID 40958316, 2025). "YTHDF3 enhances the translation of transcripts associated with tumor metastasis." (PMID 36875159, 2023). "The results of the GSEA enrichment suggest that YTHDF3 may be associated with different pathways in cells in various tumor types." (PMID 36606187, 2022). "YTHDF3, as regulator (“reader”) of m6A modification, has been reported to play an important role in tumor progression." (PMID 40406242, 2025). "m6A readers have been reported to be involved in the control of mRNA fate, and YTHDF3 has been shown to promote the progression of many tumour types, but little is known about its effects on cells under environmental cues." (PMID 40610445, 2025). "In in vitro experiments, we demonstrated that YTHDF3 promoted tumor progression in TNBC by CCK-8, colony formation assay, Transwell migration assay, and wound healing assay." (PMID 40406242, 2025). "We confirmed bioinformatically that the YTHDF3 expression was significantly higher in TNBC tumor samples than in normal samples." (PMID 40406242, 2025). "To further elucidate the role of YTHDF3 in HPV-induced immunosuppressive tumor microenvironment (ITME) formation, we demonstrated that YTHDF3, an m6A RNA reader, suppresses type I ISGs responses." (PMID 41453852, 2025). "Our experimental models demonstrated substantial depletion of these immunosuppressive elements in Ythdf3−/− TMEs, revealing that YTHDF3 deficiency reprograms the immunotolerant tumor microenvironment." (PMID 41453852, 2025). "To delineate the immunoregulatory hierarchy of the YTHDF3/m6A/STAT3 axis in tumor-immune crosstalk, we engineered Ythdf3 knockout (Ythdf3−/−) mice through CRISPR/Cas9-mediated editing and established TC-1 xenograft models." (PMID 41453852, 2025). "In this study, the expressions of WTAP, METTL14, YTHDF3 were inhibited in tumor tissues, the decrease of WTAP levels was most apparent." (PMID 39744575, 2025). "There was a significant positive correlation between PKNOX1 expression and YTHDC1 and YTHDF3 expression in 27 tumor types." (PMID 40625743, 2025). "In the NSCLC tissue, immunohistochemical analysis revealed that YTHDF3 was highly expressed in the tumor tissue as comparing with adjacent normal tissue." (PMID 38992016, 2024).
tumor (continued). "The role of YTHDF3 In ocular melanoma has been investigated, revealing its essential contribution to oncogenic capacity and tumor propagation." (PMID 39342406, 2024). "Given the critical function of m6A modification on tumor immune evasion, this study performed series of assays to test the function of m6A reader YTHDF3 on NSCLC immune evasion." (PMID 38992016, 2024). "According to reports, YTHDF3 plays a pivotal role as a crucial component of m6A methylation across various tumor types." (PMID 39372951, 2024). "Research has shown that m6A readers such as IGF2BP2, IGF2BP3, YTHDF2, and YTHDF3 are involved in tumor angiogenesis, further influencing the occurrence and development of tumors and potentially affecting the prognosis of patients with tumors to some extent." (PMID 39295872, 2024). "The RNA N6-methyladenosine (m6A) modification represents an emerging mechanism for gene expression regulation, with the active involvement of the YTH N6-methyladenosine RNA binding protein 3 (YTHDF3) in tumor progression across multiple cancer types." (PMID 39372951, 2024). "Except METTL14, YTHDF2 and YTHDF3, all m6A related genes expression were significantly different between tumor and control group." (PMID 37194014, 2023). "Among the regulatory genes, ALKBH1 and ALKBH3, which are methylation erasers, were upregulated and TRMT10C, TRMT6, TRMT61B, YTHDF2, and YTHDF3 were downregulated in tumor samples in comparison to normal tissues." (PMID 37679761, 2023). "The vascular density in metastatic tumor tissues is significantly reduced after YTHDF3 knockdown, and the expression of VEGFA and other genes is positively correlated with the expression of YTHDF3." (PMID 38053093, 2023). "When YTHDF3 expression was decreased, the effect of overexpressed cirRNA-KIAA1429 also was attenuated via depletion of Zeb1, suggesting that cirRNA-KIAA1429 cooperated with YTHDF3 to affect tumor development." (PMID 36875073, 2023). "YTHDC1, HNRNPC, HNRNPA2B1, YTHDF1, YTHDF2, and YTHDF3 all showed significantly high expression in ccRCC (all p-values < 0.0001) compared to the average overall gene expression in the tumour tissue." (PMID 36899967, 2023). "In general, YTHDF3 overexpression promoted proliferation, migration and invasion of Sk-Hep-1 and HepG2 cells in vitro and tumor growth and lung metastasis of HCC in vivo." (PMID 36471428, 2022). "We found that pyruvate and lactate level in tumor tissue were substantially decreased in Ythdf3−/− mice, compared with those in Ythdf3+/+ mice, suggesting that YTHDF3 promotes growth and progression of HCC by glucose metabolism pathway." (PMID 36471428, 2022). "In TCGA database, the YTHDF3 differential expression was analyzed between tumor and normal tissues in 27 diverse cancer types." (PMID 35755811, 2022). "Previous studies showed that the expression of m6A writers (METTL3, RBM15, WTAP), eraser (FTO, ALKBH5) and reader (YTHDF3, YTHDC2) was associated with pathological stage, tumor stage, andprognosis of patients with GC." (PMID 35977935, 2022). "In DEN and CCl4 induced HCC mice, we found the number, largest diameter of tumors, liver weight and tumor/body weight ratio of Ythdf3−/− mice were significantly decreased, compared with those of control Ythdf3+/+ mice." (PMID 36471428, 2022). "Subcutaneous tumor growth model of mice demonstrated that YTHDF3 knockdown suppressed xenografted tumor growth, tumor weight, and tumor size of HCC cells in vivo." (PMID 36471428, 2022). "Gain-of-function and loss-of-function assays demonstrated YTHDF3 promoted proliferation, migration and invasion of HCC cells in vitro, and YTHDF3 knockdown inhibited xenograft tumor growth and lung metastasis of HCC cells in vivo." (PMID 36471428, 2022). "The results showed that the YTHDF3 expression levels were higher in tumor tissues compared with those in the adjacent tissues." (PMID 36606187, 2022).
tumor (continued). "We found that high YTHDF3 expression were correlated with larger tumor diameter, capsular invasion, vascular invasion or the middle-late stage of HCC patients." (PMID 36471428, 2022). "The closed correlation implies a likely mechanism by which YTHDF3 regulates the biological functions of tumor-infiltrating immune cells in BC patients." (PMID 35755811, 2022). "Taken together, gain-of-function and loss-of-function assays uncovered that YTHDF3 promotes proliferation, migration and invasion of HCC cells in vitro and tumor growth and lung metastasis of HCC in vivo." (PMID 36471428, 2022). "To further confirm the role of YTHDF3 in cell proliferation, we also employed 3D tumor sphere formation assay experiments to re-evaluate the function of YTHDF3 in spheroid formation in several cell lines." (PMID 36606187, 2022). "The remaining cancer type had a smaller AUC, and the predictive power of YTHDF3 expression was less accurate for predicting normal and tumor outcomes (AUC < 0.7)." (PMID 36606187, 2022). "Previously, RNA functional analysis confirm that METTL14 and ALKBH5 can regulate the expression of each other, inhibit the demethylation activity of YTHDF3, and induce aberrant m6A modification to play roles in tumour angiogenesis and metastasis." (PMID 35004679, 2021). "In terms of mRNA levels, TRMT6, TRMT61A, TRMT61B, TRMT10C, YTHDF1 and YTHDF2 YTHDF3 were overexpressed in tumor sample." (PMID 34777359, 2021). "Specifically, writer VIRMA and reader YTHDF3 were significantly upregulated in SE-like TCam-2 cells, reflecting our previously published results in primary tumor samples, where both players were upregulated in SE as well." (PMID 34446080, 2021). "Generally, higher expressions of GAS5 were usually accompanied by lower expressions of YAP and YTHDF3, while lower expressions of GAS5 were associated with elevated expressions of YAP and YTHDF3 in tumor tissues from CRC patients." (PMID 31619268, 2019). "In our study, YTHDF3 is significantly elevated in CRC tumor tissues compared with that in counterpart normal tissues." (PMID 31619268, 2019). "In contrast, YTHDF3 knockdown reversed YAP-mediated promotion of CRC tumor progression, and co-transfection of YTHDF3 and GAS5 also obtained similar results." (PMID 31619268, 2019). "Tumor samples with strong VIRMA immunoexpression also displayed significantly higher YTHDF3 transcript levels (p = 0.0303) whereas those with strong YTHDF3 protein expression disclosed a trend for higher YTHDF3 transcript levels (p = 0.0724)." (PMID 30866959, 2019). "However, compared to normal tissue, WTAP (p=0.0011), METLL14 (p=0.0044) and YTH N6-Methyladenosine RNA binding protein F3 (YTHDF3) (p=0.0472) were obviously decreased in tumor tissues." (PMID 39744575, 2025). "By contrast, the role of YTHDF3 in tumor immunity remains largely unexplored." (PMID 41403953, 2025). "Furthermore, high MCMBP expression correlates with elevated levels of m6A “readers” (IGF2BP1, IGF2BP3) and “writers” (VIRMA, YTHDF3), a state thought to promote tumor progression by enhancing the stability and translation of oncogenic mRNAs." (PMID 41346611, 2025). "Notably, YTHDF3 promotes tumor angiogenesis in BC by facilitating the translation of m6A-enriched transcripts such as ST6GALNAC5, GJA1, and EGFR." (PMID 39295872, 2024). "According to reports, YTHDF3 plays an important functions in various tumor and immune processes." (PMID 38491545, 2024). "Therefore, the in vivo data indicated that YTHDF3 silencing repressed the tumor growth and promoted the CD8+ T cells infiltration." (PMID 38992016, 2024). "Similarly, YTHDF1/YTHDF3 has been implicated in increasing the translational efficiency of Integrin Subunit Alpha 1 (ITGA), one of the genes that are defined as “tumor differentiation signature”, through the recognition of the m6A site present on its 3′UTR." (PMID 39342406, 2024). "The results demonstrated that YTHDF3 silencing repressed the tumor volume and weight." (PMID 38992016, 2024).
tumor (continued). "This implies that YTHDF3 can also act as a tumor suppressor in a context-dependent manner." (PMID 36835633, 2023). "In addition, RT-qPCR and immunohistochemical staining also showed that celastrol administration downregulated Claspin, Bcl-2, METTL3, and YTHDF3 in the xenograft tumor tissues." (PMID 38110764, 2023). "Moreover, in subcutaneous tumor growth models of mice, YTHDF3 overexpression in Sk-Hep-1 cells facilitated tumor growth in vivo characterized as increasing tumor size and weight, and the percentage of Ki67 IHC staining, as compared with control group." (PMID 36471428, 2022). "We observed that YTHDF3 is widely expressed in various cancers, which may affect patient prognosis through interactions with tumor-infiltrating immune cells." (PMID 36606187, 2022). "Overexpression of YTHDF3 might inhibit the function and efficiency of NK cells in antitumor immune response, which could be one of the routes that YTHDF3 affects the tumor immune." (PMID 35755811, 2022). "The results of the MTT and 3D tumor sphere formation assay experiments showed that the proliferation abilities of H1299 and H1975 cells were reduced with YTHDF3 knocked out, while overexpressing YTHDF3 increased the proliferation of KYSR450 and PC9 cells." (PMID 36606187, 2022). "In addition, the expression level of YTHDFs in tumor tissues is also significantly different from normal tissues, and among them YTHDF3 is negatively correlates with survival rate, which is consistent with previous studies." (PMID 35095993, 2021). "We chose some regulators for RT-qPCR validation, and the qPCR results revealed that METTL3, METTL14, and FTO had consistently low expression in 33 paired samples with TCGA data, while YTHDF1 and YTHDF3 showed increased expression in tumor samples compared to adjacent tissues." (PMID 34804948, 2021). "Importantly, in the BALB/c mouse model, YTHDF3 overexpression-induced tumor progression could be partially abrogated by CENPI knockdown." (PMID 40406242, 2025). "Furthermore, some studies have shown that YTHDF3 contributes to the formation of the tumor microenvironment and could be used as an immune-related marker." (PMID 36017491, 2022). "Furthermore, tumor subcutaneous growth and lung metastasis xenograft mice models demonstrated that overexpression of YTHDF3 resulted in dramatic acceleration of the tumor growth rate and lung colonization ability, which reversed the tumor suppression resulting from GAS5 overexpression." (PMID 31619268, 2019). "Notedly, overexpression YTHDF3 promoted TNBC tumorigenesis in an m6A modification, while TNBC knockdown markedly inhibited proliferation and migratory ability of tumor cells in vitro and in vivo." (PMID 40406242, 2025). "As a prognostic marker reflecting the degree of tumor differentiation, LOXL3 is a major target of YTH domain family protein 3 (YTHDF3)." (PMID 41250755, 2025). "YTHDF3 suppressed PFKL mRNA degradation via m6A modification, subsequently promoting tumor growth and lung metastasis of HCC cells." (PMID 40406242, 2025). "Then, in the tumor tissue, the CD8+ T lymphocytes were marked by CD8 positive staining, and results indicated that YTHDF3 silencing group had higher CD8+ T cells infiltration." (PMID 38992016, 2024). "To evaluate the clinical significance of YTHDF3 in BRCA, we performed immunohistochemical (IHC) staining for YTHDF3 on tissue samples obtained from Guizhou Provincial Tumor Hospital." (PMID 39372951, 2024). "We also found a higher expression of YTHDF3 and G3BP1 in highly resistant CRPC and specific NEPC tissues, consistent with prior studies reporting higher levels of G3BP1 and YTHDF3 in different tumor tissues, and are negatively prognostic." (PMID 34939643, 2022). "Functionally, YTHDF3 promoted proliferation, migration and invasion ability of HCC cells in vitro, and promoted xenograft tumor growth and lung metastasis in vivo." (PMID 36471428, 2022).